TRPV1 (transient receptor potential cation channel subfamily V member 1)
Diseases named in the same sentence as TRPV1 in open-access papers (continued):
Sharing a sentence is not in itself a finding about the gene and the disease.
tumor (continued). "These IS-Micelles showed distinct thermotherapeutic efficacies against primary, metastatic and recurrent TNBCs, a variety of TRPV1-positive malignant human tumors including HepG2, MDA-MB-231 and PANC1 tumors, as well as small, large and orthotopic HCT-116 tumor models." (PMID 37120615, 2023). "Notably, the elevated level of TRPV1 mRNA in cisplatin-resistant tumor cells was repressed by NANOG knockdown, indicating the NANOG-dependent expression of TRPV1." (PMID 37165076, 2023). "MOC2 tumor bearing male mice had a higher percentage of DiI-positive TRPV1-IR neurons (p = 0.047), but not CGRP-IR (p = 0.272) neurons, compared to male PID14 sham mice." (PMID 36172037, 2022). "BoNT/A also did not affect tumour growth when given to mice in which TRPV1+ nociceptor neurons were genetically ablated, which suggests that its anti-tumour effectiveness depends on the presence of tumour-innervating nociceptor neurons." (PMID 36323780, 2022). "In RCC, the reduction of PD-L1 expression with CPS treatment could allow for a better anti-tumor immune response, so CPS or TRPV1 agonists could be suggested as immuno-adjuvants in the RCC therapy." (PMID 35681623, 2022). "Approximately 30% of tracer positive DRG neurons from tumor-bearing animals co-labeled with TRPV1, the majority were TRPV1 negative." (PMID 34944001, 2021). "Regardless of the reason for the difference we see in TRPV1 positivity of intra-tumoral nerves, our analysis of patient and mouse tumor samples indicates that HGSOCs are innervated and that at least one third of this innervation is sensory in nature." (PMID 34944001, 2021). "Although LLC cell inoculation resulted in a similar tumor growth in TRPV1-knockout mice (B6.129X1-Trpv1tm1JμL/J; hereafter TRPV1-KO or TRPV1–/–) and WT mice, TRPV1–/– mice failed to develop thermal hyperalgesia in the affected limb." (PMID 32960817, 2020). "Since TRPV1 expression in human GC is lacking, we first predicted its expression from Oncomine tumor database, which indicated low expression of TRPV1 in GC (data not shown)." (PMID 33008449, 2020). "These negative results are in conflict with the postulated tumor suppressor role of TRPV1 in melanoma and colon cancer." (PMID 32887395, 2020). "A study investigating mRNA expression levels of the TRP channels in human CRC tissue versus normal colon mucosa detected an increase in gene expression of TRPM8, TRPV6, and TRPV1 and a lower expression of TRPV4, TRPM4, TRPV3, TRPC6, and TRPV5 in the tumor tissues of CRC compared to normal tissues." (PMID 32182937, 2020). "At present study, we first found that the TRPV1 was lowly expressed in CRC tissues compared with CRC-adjacent tissues and normal subjects, which prompted us to speculate TRPV1 as a tumor suppressor." (PMID 31183372, 2019). "SCC-1 EphrinB1 tumors had significantly more β-III tubulin and Tau by western blot than SCC1 parental tumors suggesting increased tumor innervation; tumor expression of TRPV1 was not significantly different." (PMID 30327461, 2018). "Unfortuntely, although tumor cells express higher levels of TRPV1 than normal epithelial cells, they still do not have enough receptors to perform tumor-targeted TRPV1-mediated necrotic-type eradication." (PMID 28626428, 2017). "It has been shown that some tumor cells express the nonselective cation channel Vanilloid receptor-1 (VR1/TRPV1) TRPV1 which has a preference for Ca2+." (PMID 27754413, 2016). "Tumor colon biopsies, used for comparison in the present study, express TRPV1 and TRPA1 local mRNA gene expression but do not exhibit significant change in their gene expression levels compared to non-inflamed controls." (PMID 25265225, 2014). "Ablation of TRPV1(+) neurons also had no further effect on paw tumor volume in mice with SCC treated with IB4-SAP." (PMID 24524628, 2014).
tumor (continued). "We propose TRPV1 as representing a promising target for development of pharmacological therapies against AEA-triggered endothelial cell functions, including their stimulatory effect on tumor-angiogenesis." (PMID 25395667, 2014). "Therefore, our study suggests TRPV1 to be a promising therapeutic target for various AEA-related pathologies such as cardiovascular diseases and tumor-angiogenesis." (PMID 25395667, 2014). "However, upon more detailed examination, the lower TRPV1 transcript levels across different tumour grades did not demonstrate statistical significance within individual groups." (PMID 40243844, 2025). "For example, the CBD-induced generation of ROS via TRPV1 activation could affect both non-tumor and tumor cells equally at anti-neoplastic doses." (PMID 38730738, 2024). "Furthermore, TRPV1 agonists increase IL-17 secretion in control mice, but not in tumor-bearing mice." (PMID 37371563, 2023). "Importantly, TRPV1 inhibition using the AMG9810, a potential pain-reliever, could sensitize resistant tumor to cisplatin by repressing anti-apoptotic properties." (PMID 37165076, 2023). "Importantly, the TRPV1 blockade using SB705498 or TRPV1 knockdown effectively inhibited the in vivo stressful HSP70 expression at tumor section, together without distinct influence on normally expressed HSP70." (PMID 37120615, 2023). "TRPV1 blockade inhibits hyperthermia-induced calcium influx and subsequent nuclear translocation of HSF1, which selectively suppresses stressfully overexpressed HSP70 for enhancing thermotherapeutic efficacy against a variety of primary, metastatic and recurrent tumor models." (PMID 37120615, 2023). "To demonstrate that TRPV1 blockade might enable the manipulation of tumor stroma via suppressing HSF1-mediated TGFβ1 upregulation, we thus firstly investigated the influence of TRPV1 blockade on HSF1 distribution in the PANC02 tumor cells upon hyperthermia using immunofluorescence staining." (PMID 37120615, 2023). "Furthermore, the study found that TRPV1 protein level in DRG was increased in wild-type mice but not in TNFR2−/− mice with tumor." (PMID 36438444, 2022). "Transient receptor potential cation channel subfamily V, member 1 (TRPV1), a non-selective cation channel, plays multiple roles in tumorigenesis and tumor development, including tumor cell proliferation, death, and metastasis as well as the response to therapy." (PMID 35402237, 2022). "Our results are in agreement to a prior study in which pretreatment with the less potent TRPV1-agonist capsaicin facilitated the metastasis of 4T1 tumor in the lung and heart, while in lower, non-desensitizing doses, it decreased the frequency of lung metastases." (PMID 34336669, 2021). "TRPV1 is also expressed in several neoplasms, among which primary brain tumours, pancreatic, breast, prostate and squamous cell carcinomas of the human tongue, although its role in the tumour evolution is still not so clear." (PMID 34943903, 2021). "Future experiments should aim to find a combination of CAPS and various PAMs that might result in tumor regression in vivo without detrimental effects on the normal non-transformed cells also expressing TRPV1." (PMID 28640864, 2017). "Thus, in prostatic adenocarcinoma, TRPV1 and TRPV6 are overexpressed with respect to healthy prostatic tissues, and their expression levels correlate strictly with Gleason score, pathological stage, extraprostat extension and tumor grades." (PMID 22523714, 2012). "Given that TRPV1 is predominantly expressed in sensory neurons, indiscriminate inhibition may result in off-target effects on peripheral sensory fibers not involved in tumor biology." (PMID 41009819, 2025). "The dysregulation of both ‘classical’ (CB1 and CB2) and ‘non-classical’ (TRPV1 and GPR55) endocannabinoid receptors in EC may provide insights into the variable effects of endocannabinoids observed in different tumour models." (PMID 40243844, 2025).
infection (45 papers, 2011 to 2026). The state of being infected such as from the introduction of a foreign agent such as serum, vaccine, antigenic substance or organism. "In this review, we explore the role of TRPV-1 channel in the infection, susceptibility, pathogenesis, and treatment of SARS-CoV-2 infection." (PMID 34805220, 2021). "TRPV1 sensory neurons have been implicated in diverse cellular and physiological processes, including the intestinal response to infection." (PMID 34043943, 2021). "PIV3 infection caused a phenotypic switch in tracheal nodose Aδ “cough receptors” such that nearly 50% of neurons began to express, de novo, TRPV1 mRNA." (PMID 27213574, 2016). "Deficiency in TRPV1 significantly increased the bacterial burden at the peak of infection." (PMID 38109366, 2023). "We observed that inhibiting TRPV1 with specific TRPV1 antagonist SB-366791 reduces infection in vivo." (PMID 41596312, 2026). "We investigated survival after intranasal infection with 6A to determine the differential TRPV1 function of the olfactory nerve or the trigeminal nerve." (PMID 40823821, 2025). "We used a mouse model to demonstrate the nose-to-brain invasion of S. pneumoniae and to elucidate how TRPV1 on the two sensory nerves is involved in the infection." (PMID 40823821, 2025). "Particularly, TRPV1+ nociceptive neurons, known for transmitting electrical signals from sites of infection or inflammation to neighboring skin through antidromic neuron activation, contribute to an “anticipatory immunity”18." (PMID 38902277, 2024). "Immunohistochemistry of tissue sections 1 day after infection suggested that TRPV1−/− mice had significantly more Ly6G + cells in the infected region than those in the infected region of WT mice." (PMID 38129779, 2023). "Reflective of the increased C. rodentium burden, expression of the antimicrobial gene RegIIIγ was significantly increased during infection, and further enhanced in infected TRPV1-/- compared to WT mice 10 days p.i.." (PMID 38109366, 2023). "In our study, when TRPV1 was selectively knocked out, the animal improved the clearance of S. aureus, and infection was better controlled, suggesting that TRPV1+ neurons play a negative regulatory role in local immunity." (PMID 38129779, 2023). "Sorted colonic BECs, lymphatic endothelial cells (LEC), and stromal cells express Trpv1 mRNA at baseline with infection induced upregulation of Trpv1 in BECs." (PMID 38109366, 2023). "Infection of WT and TRPV1-/- mice significantly increased colonic Il6 and Tnfα expression compared to uninfected controls." (PMID 38109366, 2023). "Fecal and colonic C. rodentium were significantly increased in TRPV1-/- compared to WT mice 10 days post-infection (p.i.), with both TRPV1-/- and WT mice clearing the infection by 29 days p.i.." (PMID 38109366, 2023). "Collectively these data identify a novel role for TRPV1 in the regulation of neutrophil recruitment to the colon during infection with enteric bacterial pathogens." (PMID 38109366, 2023). "Colonic neutrophils also exhibited high levels of Trpv1 transcripts that were downregulated upon infection." (PMID 38109366, 2023). "We labeled MPO with luminol, and the bioluminescence results showed significantly higher local MPO activity in TRPV1−/− mice than that in WT mice 1 day after infection." (PMID 38129779, 2023). "Our qPCR data suggests that recruited colonic T cells during C. rodentium infection upregulate Trpv1 mRNA transcripts compared to LB treated mice; however, it is unclear if TRPV1 protein on T cells is altered during infection." (PMID 38109366, 2023). "To examine the involvement of the TRPV1 channel in the mechanism of capsaicin-induced antitumor effect and AMPK activation, we knocked down TRPV1 expression by infection with lentiviral viruses carrying small hairpin RNA (shRNA)." (PMID 35214061, 2022).
infection (continued). "Similar time courses were observed, and around 70% of mice finally developed lethal infection among all groups in the mono-infection model (wild type; 65%, TRPV1 KO; 62%, TRPV4 KO; 75%, respectively)." (PMID 34804016, 2021). "When the mice were pre-infected with IAV, more than 70% of TRPV1 KO mice eventually developed lethal infection." (PMID 34804016, 2021). "Following infection or injury, TRPV1 activity is sensitized by various pro-inflammatory mediators such as nerve growth factor (NGF), prostaglandins and bradykinin, which then leads to thermal hyperalgesia." (PMID 33668926, 2021). "Lastly, treatment with agonists that down-regulate or inactivate TRPV-1 can have a beneficial action on impaired lung functions and clearance of infection." (PMID 34805220, 2021). "Further evidence for a role of TRPV1+ nociceptors in barrier tissues is found in the recent studies of infection in skin and lungs." (PMID 34200205, 2021). "To this end, we applied lentiviruses infection to make TRPV1-overexpressed BGC823 cells and TRPV1-knockeddown MKN45 cells." (PMID 33008449, 2020). "Taken together with our earlier hyperthermia study, these data suggest that CVB relies on TRPV1 activity for efficient infection." (PMID 32231022, 2020). "Mortality was markedly prevented by TRPV1 ablation as 90% of the TRPV1KO mice survived infection in contrast with WT animals (19% survival)." (PMID 31223430, 2019). "TRPV1 is an essential component of the cellular signalling mechanisms through which tissue damage or infection produces thermal hyperalgesia and pain hypersensitivity is primarily expressed on small, unmyelinated sensory neurons in the trigeminal ganglia." (PMID 30841522, 2019). "TRPV1 has a significant role in the maintenance of core body temperature, at least in mammals and during infection and inflammation." (PMID 29196683, 2017). "Some reports also suggest that TRPV1 is involved in the regulation of core body temperature, especially in conditions of infection and/or inflammation." (PMID 29196683, 2017). "Our data show that the virus MOI and duration of infection are important factors in TRPV1 and ASIC3 expression modulation in both epithelial and neuronal cells." (PMID 28187208, 2017). "At 36 hpi (not shown) or in some cases at the highest MOIs tested for each virus, infection resulted in cell death with concomitant drops in TRPV1 and ASICS mRNA levels." (PMID 28187208, 2017). "After infection of TGNs with the resultant lentiviral particles for 7 days, monitoring the total expression of TRPV1-DsRed by SDS-PAGE/Western blotting showed a band with a molecular size ~125 k." (PMID 26888187, 2016). "Early upregulation of TRPA1 and TRPV1 expression in differentiated IMR-32 neuroblastoma cells is evidenced at 2 to 4 hours post-RV HRV-16 infection." (PMID 25644504, 2015). "TRPV1 is expressed, functional and active within cells relevant to inflammation, infection and immunity." (PMID 23800232, 2013). "Given that capsaicin-mediated TRPV1 activation increased infection, we sought to determine whether blocking TRPV1 would affect CVB3 infection in vivo." (PMID 41596312, 2026). "The current finding can bring new strategies against infection targeting TRPV1." (PMID 40823821, 2025). "Interestingly, infection of TRPV1-/- mice with C. rodentium resulted in significantly fewer colonic neutrophils 10 days post-infection compared to WT mice." (PMID 38109366, 2023). "Moreover, TRPV1−/− mice showed a significant improvement in body weight maintenance as well as core body temperature maintenance during infection compared to those of WT mice." (PMID 38129779, 2023). "Although it is unclear what TRPV1 agonists would be present in an in vitro culture, these differences could also be attributed to unique ligands present during infection-induced inflammation in vivo compared to in vitro." (PMID 38109366, 2023).
infection (continued). "Similarly, Cxcl2 and Cxcl3 expression were increased during infection; however, there was a significant defect in TRPV1-/- mice to express these chemokines 29 days p.i. compared to WT mice." (PMID 38109366, 2023). "Similarly, flow cytometry results 1 day after infection suggested a higher number of subcutaneously recruited neutrophils in TRPV1−/− mice than that in WT mice." (PMID 38129779, 2023). "In addition, the expression of many sensory nerve markers, including Tac1 and TRPV1, and the lung fiber innervation patterns themselves are plastic and can be modulated by inflammation and infection." (PMID 35365503, 2022). "There was a significant difference between TRPV1 KO and wild type in the mono-infection model." (PMID 34804016, 2021). "Within the epidemiological area, the identification of TRPV-1 genetic polymorphisms could have important implication in SARS-CoV-2 susceptibility, infection and spread." (PMID 34805220, 2021). "Because TRPV1 inhibition via SB-366791 significantly limits CVB infection, we hypothesize that TRPV1 stimulators such as heat or capsaicin amplify infection by inducing mitochondrial depolarization which leads to mitochondrial fission." (PMID 32231022, 2020). "Infection with Plasmodium berghei ANKA decreased TRPV1 expression in the brain." (PMID 31223430, 2019). "Nevertheless, several studies reported that the ablation of TRPV1+ neurons might be beneficial in the treatment of inflammatory disorders and some infection." (PMID 31681615, 2019). "In contrast to wild type mice however, TRPV1-deficient mice did not exhibit visceral hypersensitivity following infection with SΦ874." (PMID 29739958, 2018). "Interestingly, the expression of TRPV1-K822R in DRG neurons of wild-type mice significantly reduced thermal hypersensitivity induced by carrageenan injection as compared to the infection by AAV-TRPV1, although the effect was moderate." (PMID 29670121, 2018). "In addition, we determined that the cation channel, TRPV1, mediates thermal hyperalgesia during infection, further adding to the molecular mechanisms, beyond bacterial-induced modalities, of pain during infection." (PMID 29295977, 2018). "Consistent with this hypothesis we noted that by day 4 of PIV3 infection there was an increase in TRPV1 expression in jugular ganglion neurons." (PMID 27213574, 2016). "Therefore, we speculate that skin macrophages act as “sentinels”, and may be regulated by TRPV1+ neurons before neutrophils during infection." (PMID 38129779, 2023). "Finally, treatment with agonists that down-regulate or inactivate TRPV-1 may have a beneficial effect on impaired lung function, and clearance of infection." (PMID 34805220, 2021). "However, it does shed light on the role of CGRP in immune cell infiltration after wounding, which may be induced in other models of wound healing via TRPV1 activation, as shown in infection." (PMID 34200205, 2021). "Thus, TRPM8 activation by either cold or menthol appears to drastically attenuate infection, and this may be a product of TRPV1 antagonism." (PMID 32231022, 2020). "TRPV1 could be sensitized during infection through several mechanisms that require further study." (PMID 29295977, 2018). "Moreover, overnight incubation of mouse DRGs with PI-IBS supernatant resulted in an increased Ca2+ response to capsaicin, confirming that the PI-IBS micro-environment, even 2 years after the infection, contains mediators that activate nociceptive afferents and sensitize TRPV1." (PMID 29051514, 2017). "Studies have confirmed that PAR2 can regulate TRPV1 to participate in post-infection cough, and PAR2 can also regulate the cough representation of guinea pigs by affecting TRPV1." (PMID 40001511, 2025). "The selective genetic ablation of TRPV1+ sensory neurons inhibited CGRP release, restoring neutrophil recruitment to infection sites." (PMID 41011451, 2025).